TLR3 (toll like receptor 3)
Diseases named in the same sentence as TLR3 in open-access papers (continued):
Sharing a sentence is not in itself a finding about the gene and the disease.
glaucoma (3 papers, 2021 to 2025). Increased pressure in the eyeball due to obstruction of the outflow of aqueous humor. "The activity of TLR3 involved in the recognition ofnucleic acids released from damaged cells is mainly associatedwith the early stage of glaucoma (Soto, Howell, 2014).However, the association of polymorphism of this gene withglaucoma is controversial in the literature." (PMID 40144379, 2025). "The aim was to analyze the association of the TLR2 (rs5743708), TLR3 (rs3775291), TLR4 (rs4986790, rs4986791) and TLR6 (rs5743810) polymorphisms with primary open-angle glaucoma in patients of Western Siberia." (PMID 40144379, 2025). "In glaucoma, TLR3 andTLR4 have been shown to initiate nephroptosis – the regulatedproinflammatory lytic form of necrotic cell death characterizedby cell swelling followed by rupture of the plasma membranewith the release of cellular contents." (PMID 40144379, 2025). "Mutations in optineurin (OPTN) associated with primary open angle glaucoma (E50K) reduced the phosphorylation of IRF3 and IFNα/β release assays in response to poly (I:C) stimulation of TLR3." (PMID 34366851, 2021). "In optic nerve head astrocytes, stimulation of TLR3 led to a transfer of cellular ATP from cytoplasmic to extracellular compartments, suggesting inflammatory signaling can strain cellular energetics in relationship to glaucoma." (PMID 34366851, 2021). "Studies of anatomy have reported elevated levels of TLR2, TLR3, and TLR4 in microglia and astrocytes in the retina of glaucoma patients." (PMID 34561506, 2021).
hypothyroidism (3 papers, 2023 to 2024). Abnormally low levels of thyroid hormone. "Take hypothyroidism as another example, the protein encoded by TLR3 is a member of the Toll-like receptor (TLR) family and plays a fundamental role in pathogen recognition and activation of innate immunity." (PMID 38143258, 2024).
inflammatory skin disease (3 papers, 2018 to 2023). Inflammatory skin disorders covers a broad category that includes many conditions ranging in severity, from mild itching to grave medical health complications These disorders are common in people of all ages and races. "Co-deletion of TRAIL-R and TLR3 in Tnfr1KO;Hoil-1E-KO mice resulted in slightly milder skin lesions at day 70, yet these mice still succumbed to inflammatory skin disease with a median survival of 77 days." (PMID 30254289, 2018). "Of further importance, these actions of DMG-Na were observed in all three in vitro keratinocyte systems, modeling a wide array of inflammatory skin diseases, irrespective of whether the inflammation was induced by TLR3 stimulation, the combination of INFγ and TNFα, or UVB irradiation." (PMID 37511024, 2023).
Kaposi's sarcoma (3 papers, 2015 to 2022). A malignant neoplasm characterized by a vascular proliferation which usually contains blunt endothelial cells. "Furthermore, opposing roles of RNA receptors TLR3 and RIG-I in the inflammatory response to dsRNA has also been shown in a Kaposi's sarcoma cell line SLK." (PMID 26208481, 2015).
kidney cancer (3 papers, 2022 to 2023). Primary or metastatic malignant neoplasm involving the kidney. "Our results showed that the deletion of risk genes, such as TLR3 and LY96, were lethal for kidney cancer cells." (PMID 36189275, 2022).
Lewis lung carcinoma (3 papers, 2016 to 2020). "Another study reported that primary Lewis lung carcinoma (LLC)-derived EVs activated toll-like receptor 3 (TLR3) in lung epithelial cells." (PMID 32585976, 2020).
liver cirrhosis (3 papers, 2017 to 2020). "Three other TLR3 SNPs (rs5743313, rs5743314, and rs111611328) were also associated with HCV-related end-stage liver disease progression (liver cirrhosis and HCC)." (PMID 28127569, 2017). "In previous reports, TLR3 polymorphisms rs1879026, rs3775296, rs3775291, rs5743305 have been associated with the outcome of hepatitis C virus (HCV) and HBV infection, and the development of consequential liver cirrhosis and HCC primarily in Asian populations." (PMID 30143709, 2018). "Eight TLR3 SNPs were analyzed in 563 patients with HCV, which consisted of 437 patients with chronic HCV infections, 88 with HCV-induced liver cirrhosis, and 38 with HCC." (PMID 28127569, 2017).
mucocutaneous leishmaniasis (3 papers, 2012 to 2020). The most common form of leishmaniasis that is transmitted through the bite of female phlebotomine sand flies or after exposure to leishmania parasites. "Another striking example is the discovery of a double-stranded RNA virus in Leishmania parasites (LRV), which is responsible for the exacerbation of the severity of mucocutaneous leishmaniasis via a TLR3/IFN-I-dependent proinflammatory response." (PMID 32265335, 2020).
orchitis (3 papers, 2019 to 2020). Inflammation of one or both testes due to viral or bacterial infections. "showing how TLR3 upregulation contributed on the modulation of inflammatory cytokine generation during orchitis in testicular cells." (PMID 33488524, 2020). "In addition, circRNA‐9119 is known to sponge both miR‐26a and miR‐136, which, in turn, regulate TLR3 and inducible gene I, the two essential molecules in orchitis." (PMID 32452125, 2020). "Moreover, RIG-I and TLR3 contributed to the modulation of poly I:C-triggered inflammatory cytokine generation during orchitis in testicular cells." (PMID 31195953, 2019). "circRNA-9119 acted as a sponge for both miR-26a and miR-136, which in turn target TLR3 and RIG-I, respectively, the two essential molecules in orchitis." (PMID 31195953, 2019). "Therefore, TLR3 and RIG-I upregulation may contribute to the pro-inflammatory activities of circRNA-9119 in orchitis." (PMID 31195953, 2019).
osteosarcoma (3 papers, 2023 to 2025). A usually aggressive malignant bone-forming mesenchymal neoplasm, predominantly affecting adolescents and young adults. "Using osteosarcomas and rhabdomyosarcomas as models, we show that TLR3 efficiently drives tumor cell death in vitro and induces tumor regression in vivo." (PMID 37414800, 2023). "Moreover, our results reveal that it is possible to restore TLR3 expression in aggressive tumor cells via IFN-1 pre-treatment, and that the addition of Poly(I:C) dsRNA is then sufficient to trigger TLR3-induced cell death in vitro and in vivo, notably in osteosarcoma models." (PMID 37414800, 2023).
parasite infection (3 papers, 2016 to 2024). "Despite the functions of TLRs in the parasitic infections have been extensively reported, few studies have addressed the role of TLR3 in the immune response to Schistosoma japonicum infections." (PMID 38172683, 2024).
periodontal disease (3 papers, 2015 to 2025). "While maintaining pluripotency through increased NANOG expression in non-inflammatory conditions to protect the cells from senescence, the inflammatory microenvironment and DAMPS in periodontal diseases can increasingly prime the TQ-endorsed TLR3." (PMID 35563755, 2022). "TLR3 stimulation in combination with IL-1β has previously been shown to initiate CCL20 upregulation in human gingival fibroblasts in periodontal disease, and our results indicate that this cellular mechanism can also be important in IBD." (PMID 26536229, 2015). "The observed downregulation of TLR3 and TLR10 in inflamed PDLSCs suggests a shift from anti-inflammatory functions of the cells to a bacterially driven pro-inflammatory phenotype, which is characteristic of periodontal disease progression." (PMID 40136681, 2025).
prostate adenocarcinoma (3 papers, 2015 to 2025).
pulmonary diseases (3 papers, 2009 to 2022). "FOXO is activated in patients with pulmonary diseases and its deficiency results in suppression of TLR3-dependent epithelial innate immune function and increased pathogen uptake." (PMID 39086962, 2022). "Thus, an understanding of TLR3 activation should provide insight into the mechanisms underlying virus-induced exacerbations of pulmonary diseases." (PMID 19486528, 2009). "Tracheobronchial epithelial cells (TBEC) and AMs from four smokers and four non-smokers without lung disease were cultured with or without Poly(I:C) (PIC) (a TLR3 agonist) or LPS (a TLR4 agonist) for 4, 24 and 48 h." (PMID 29940963, 2018).
pustular psoriasis (3 papers, 2014 to 2018). "Mutation in σ1C discrupts the endosomal translocation of TLR-3 (toll-like receptor 3) and causes a severe autoinflammatory skin disorder called pustular psoriasis." (PMID 24975939, 2014). "Furthermore, mutations in the AP1S3 gene, encoding the AP-1 complex subunit σ1C, which lead to a disruption of the endosomal translocation of toll-like receptor 3 (TLR3), are associated with pustular psoriasis." (PMID 29963046, 2018). "In further support of a role for aberrant IL-1 signalling in pustular psoriasis, the disease is associated with pathogenic mutations in AP1S3, silencing of which has been shown to disrupt the endosomal translocation of Toll-like receptor 3 (TLR3), leading to impaired IFNβ induction." (PMID 26573299, 2016).
renal carcinoma (3 papers, 2019 to 2020). A carcinoma arising from the epithelium of the renal parenchyma or the renal pelvis. "For instance, treatment of human renal cancer cell lines with the synthetic TLR3 agonist poly(I:C) induced IFN-1β release and caused cell death." (PMID 30824859, 2019).
renal cell carcinoma (3 papers, 2016 to 2023). "Induction of TLR3 by its ligand poly(IC) has also been described to reduce viability in tumor cells of renal cell carcinoma and metastatic colorectal cancer." (PMID 27941651, 2016).
respiratory syncytial virus infection (3 papers, 2013 to 2025). "In mice model of respiratory syncytial virus infection, PG1505 purified from lactobacteria enhanced innate respiratory antiviral immune response and increased antiviral resistance via activation of Toll-like receptor-3 (TLR-3)." (PMID 38178223, 2024).
retinal degeneration (3 papers, 2012 to 2021). Degeneration of the retina. "TLR3 has been implicated to be responsible for retinal degeneration in a mouse model of cone-rod dystrophy as well as in light-induced degeneration." (PMID 34445096, 2021). "Ambati and colleagues have reported that administering siRNAs greater than 21 bp can actually lead to retinal degeneration in animal models, through Toll-like receptor-3 (TLR3), but TLR7 and TLR8 are more commonly accepted as mediating the innate immune response to dsRNA." (PMID 23077406, 2012).
sarcoma (3 papers, 2021 to 2023). A usually aggressive malignant neoplasm of the soft tissue or bone. "Here, by integrating public transcriptomic data of pediatric tumors, we unveil that high TLR3 expression is largely associated with a better prognosis in childhood sarcomas." (PMID 37414800, 2023). "Although this finding needs to be validated using independent cohorts of patients, it suggests that blockage of TLR3 functionality might also be considered as a risk factor for pediatric sarcomas." (PMID 37414800, 2023). "Thus, our results demonstrate the therapeutic potential associated with the targeting of TLR3 in pediatric sarcomas, but also the need to stratify patients eligible for this clinical approach with respect to the TLR3 variants expressed." (PMID 37414800, 2023). "By integrating transcriptomic data, we established here the prognostic value of TLR3 expression in several pediatric, adolescent and young adult sarcomas." (PMID 37414800, 2023). "Here, we show that the level of TLR3 expression has a good predictive value in childhood sarcomas, and notably in FP-RMS and OS." (PMID 37414800, 2023). "Using publicly available transcriptomic datasets, we analyzed the prognostic impact of TLR3 expression in cohorts of patients with sarcomas." (PMID 37414800, 2023). "However, when screening sarcoma cells to define the role of TLR3, we observed that a fraction of RMS cell lines were resistant to IFN-1/Poly(I:C) treatment." (PMID 37414800, 2023). "We then aimed at defining whether TLR3 activation by synthetic dsRNA, namely Poly(I:C), was sufficient to trigger sarcoma cell death." (PMID 37414800, 2023). "Furthermore, an exogenous supply of type I IFNs was shown to restore chemotherapeutic responses to DOX in Toll-like receptor 3 (Tlr3)−/− sarcomas growing in mice, supporting the use of IFN-β in augmenting DOX efficacy." (PMID 34632049, 2021). "Hence, TLR3 expression is largely associated with a favorable outcome notably in pediatric and AYA sarcomas, suggesting that it may function mostly as a death receptor in those tumor cells." (PMID 37414800, 2023).
Splenomegaly (3 papers, 2012 to 2022). Abnormal increased size of the spleen. "Stimulation of TLR3 resulted in a significant reduction in viral loads and prevented virus-induced splenomegaly as well as the onset of lethal erythroleukemia." (PMID 25539593, 2014). "However, 10-mo-old DNase II−/−Ifnar1−/− mice have been reported to develop splenomegaly and produce antinuclear antibodies in a STING- or AIM2-independent manner; instead, Unc93b, which regulates the localization of several TLRs (e.g., TLR3, TLR7, and TLR9) to the endosome, is required." (PMID 34901991, 2022).
uveitis (3 papers, 2012 to 2025). An inflammatory process affecting a part of or the entire uvea. "We have previously reported that, when activated by Toll-like receptor 3 (TLR3) and TLR4 ligands, retinal astrocytes (RACs) are able to function as antigen-presenting cells to re-activate uveitogenic T cells and allow responder T cells to induce uveitis in mice." (PMID 22808176, 2012).
adrenal cortical carcinoma (2 papers, 2016). "With respect to adrenal autoimmunity, TLR3-expressing adrenocortical carcinoma cells stimulated with poly(I:C) along with IFN-γ or tumor necrosis factor α display significant rise in production of CXCL10, a chemokine involved in autoimmune adrenal failure." (PMID 26318769, 2016).
alcoholic liver diseases (2 papers, 2024 to 2025). A disorder caused by damage to the liver parenchyma due to alcohol consumption. "In the alcoholic liver disease, there is evidence that TLR2 deficiency significantly alleviates damage, while TLR3 deficiency, on the contrary, aggravates it." (PMID 39769138, 2024).
amyloidosis (2 papers, 2020 to 2021). A disorder characterized by the localized or diffuse accumulation of amyloid protein in various anatomic sites. "Although the role of CYP4V2 in amyloidosis is currently unclear, activated TLR3, along with some members of the toll-like receptors family, can induce Aβ uptake or inflammatory response during the AD progression." (PMID 30361487, 2021).
autism (2 papers, 2021 to 2022). Persistent deficits in social interaction and communication and interaction as well as a markedly restricted repertoire of activity and interest as well as repetitive patterns of behavior. "Thus, in addition to research into mechanisms of autism-like behavior, BTBR mice can be used as a model of TLR3/TLR4-induced neuroinflammation and a unique model for finding and evaluating the effectiveness of various TLR antagonists aimed at reducing neuroinflammation." (PMID 36555219, 2022).
autoimmune thyroid disease (2 papers, 2016 to 2021). Inflammatory disease of the thyroid gland due to autoimmune responses leading to lymphocytic infiltration of the gland. "TLR3 is also expressed in both thyroid follicles and inflammatory cells of iodine-induced NOD.H-2h4 mice, a classic model of spontaneous autoimmune thyroiditis." (PMID 28018345, 2016).
basal cell carcinoma (2 papers, 2024). A carcinoma involving the basal cells. "Notably, the TLR7 agonist imiquimod is used to treat basal cell carcinoma and encouraging results have been observed by simultaneously targeting TLR3 and TLR7." (PMID 38476365, 2024).
Behçet's disease (2 papers, 2011 to 2022). "An in vitro investigation showed that retinal endothelial cells produced sE-selectin, sICAM-1 and IFN-β in response to TLR3 activation by poly I:C, implying that TLR3 activation may play a role in raised inflammatory markers in Behcet disease and idiopathic uveitis." (PMID 38983565, 2022).
biliary atresia (2 papers, 2011 to 2023). A rare, biliary tract disease characterized by progressive obliterative cholangiopathy of the intra- and extrahepatic bile ducts, occurring in the embryonic/ perinatal period, leading to severe and persistent neonatal jaundice and acholic stool. "They observed that TLR3 signaling led to the expression of CCL5 via NF-κB and IRF3 in bile duct cells, and they suggested the involvement of this signaling pathway in biliary atresia pathogenesis." (PMID 37511764, 2023).
bladder cancer (2 papers, 2020 to 2024). "Activation of the TLR3/NF-κB pathway significantly upregulated MHC-I gene expression, thereby inhibiting immune escape and augmenting immunotherapy in muscle-invasive bladder cancer." (PMID 38627815, 2024).
brain injury (2 papers, 2017 to 2022). Acute and chronic (see also brain INJURIES, CHRONIC) injuries to the brain, including the cerebral hemispheres, CEREBELLUM, and brain STEM. "Sevoflurane pretreatment can activate TLR3 and TLR9 signaling pathway, upregulate TLR3 expression and TRIF expression, decrease TLR9 expression, and downregulate NF-κB expression and inhibited the production of S100β and IL-6, thereby lessening CPB inflammation-induced brain injury." (PMID 29445737, 2017).
Cachexia (2 papers, 2015 to 2021). Severe weight loss, wasting of muscle, loss of appetite, and general debility related to a chronic disease. "The role of IL-1β in cachexia is further demonstrated by cachexia studies in which MyD88, which is the universal adaptor protein to all Toll-like receptors (TLRs; except TLR3) and the interleukin 1 receptor family, is implicated in the pathogenesis of cancer cachexia." (PMID 34439145, 2021). "Chronic Poly I:C treatment, via activation of Tlr3 and the RIG-I-like receptors, results in the production of IL-6 and IFNγ that can, when provided chronically as a model for cachexia, lead to a progressive weight loss." (PMID 25856311, 2015).
cervical disease (2 papers, 2012 to 2025). "TLR3 expression has been reported in verruca vulgaris and molluscum contagiosum and associated with HPV‐related cervical disease." (PMID 41211638, 2025).
chorioamnionitis (2 papers, 2011 to 2012). A morphologic finding indicating inflammation of the fetal sac membranes. "For instance, of the 6 women with chorioamnionitis none had increased levels of TLR3, only 1 had increased levels of TLR7, and 2 for TLR8." (PMID 22848646, 2012).
chronic obstructive pulmonary disease (2 papers, 2011 to 2018). A chronic and progressive lung disorder characterized by the loss of elasticity of the bronchial tree and the air sacs, destruction of the air sacs wall, thickening of the bronchial wall, and mucous accumulation in the bronchial tree. "The objective of the study is to explore the role of respiratory syncytial virus Toll-like receptor 3 (TLR3)-mediated immune response in the pathogenesis of acute exacerbations of chronic obstructive pulmonary disease (AECOPD)." (PMID 29264743, 2018).
chronic pancreatitis (2 papers, 2011 to 2024). A chronic inflammatory process causing damage and fibrosis of the pancreatic parenchyma. "Consistently, Gene Set Enrichment Analysis (GSEA) revealed the activation of the TLR3/4 signaling pathway in chronic pancreatitis." (PMID 38816352, 2024).
clonorchiasis (2 papers, 2023). Infection of the biliary passages with clonorchis sinensis, also called Opisthorchis sinensis. "TLR3 deficiency resulted in severe clonorchiasis in C. sinensis-infected mice compared with WT mice." (PMID 37167198, 2023).